PDK4 (pyruvate dehydrogenase kinase 4)
Diseases named in the same sentence as PDK4 in open-access papers (continued):
Sharing a sentence is not in itself a finding about the gene and the disease.
ovarian tumour (1 paper, 2020). "By qPCR analyses, significantly higher PDK4 expression in ascites-derived tumour cells, compared to primary ovarian tumour cells and the normal ovarian epithelial cell line, HOSE 96-9-18." (PMID 32390009, 2020). "Furthermore, we observed upregulation of the mitochondrial gatekeeping enzyme, PDK4, in not only ascites-derived cancer cells relative to primary ovarian tumour cells but also in tumourspheres and the ALDH+CD44+ subset." (PMID 32390009, 2020).
overnutrition (1 paper, 2018). An imbalanced nutritional status resulting from excessive intake of nutrients. "During nutrient abundance (e.g., overnutrition), and in insulin-resistant or diabetic states, FoxO1 modulates the oxidation of glucose via pyruvate dehydrogenase kinase 4 (PDK4)." (PMID 29484207, 2018).
paroxysmal AF (1 paper, 2022). "The protein expression and activity of PDK-1 and PDK-4, which inactivate the PDH complex in the mitochondria, were increased and accompanied by a significant downregulation of PDH in canine models of paroxysmal AF." (PMID 36139490, 2022). "In a canine model, paroxysmal AF increased the lactic acid content and the expressions and activities of PDK-1, PDK-4, and LDHA and the decreased the expressions of PDH and citrate synthase and the AMP/ATP ratio in canine LA." (PMID 36139490, 2022).
prostate adenocarcinoma (1 paper, 2022). "In conclusion, we show that miR-32 promotes MYC-induced prostate adenocarcinoma and identifies PDK4 as a PC-relevant metabolic target of miR-32-3p." (PMID 35228520, 2022).
pulpitis (1 paper, 2023). Inflammation of the dental pulp. "Since LPS has been widely proven to stimulate inflammation in human tissues, including dental pulp, we indicated that PDK4 may participate in the progression of pulpitis." (PMID 37275855, 2023). "Collectively, these results show that PDK4 may serve as a key resistance factor for ferroptosis via various pathways and may be involved in pulpitis progression." (PMID 37275855, 2023). "According to previous studies, LINC00943 and PDK4 may reveal the correlation between ferroptosis and pulpitis; however, their interaction has not yet been discussed." (PMID 37275855, 2023).
renal fibrosis (1 paper, 2025). A final common manifestation of a wide variety of chronic kidney diseases characterized by glomerulosclerosis and tubulointerstitial fibrosis. "In this study, we observed that ZGP, YGP, and its components modulated PPARA and its downstream genes, PDK4, to influence renal fibrosis and glucose metabolism." (PMID 40417738, 2025).
Right ventricular hypertrophy (1 paper, 2024). In this case the right ventricle is more muscular than normal, causing a characteristic boot-shaped (coeur-en-sabot) appearance as seen on anterior- posterior chest x-rays. "However, right ventricular hypertrophy stimulation activates PDK4, promoting glycolysis and causing a decline in right ventricular function." (PMID 38547044, 2024).
sarcopenia (1 paper, 2025). Progressive decline in muscle mass due to aging which results in decreased functional capacity of muscles. "Although this study suggests that PDK4 is involved in the molecular mechanism of sarcopenia-like myotube thinning caused by SASP, it remains to be clarified how PDK4 causes mitochondrial dysfunction and its relationship with SASP factors." (PMID 40623060, 2025).
skin cancer (1 paper, 2014). "Most notably, we observed dramatically decreased PDK4 expression in the majority of cancer types examined, including breast, colorectal, lung, lymphoid, ovary, and skin cancers." (PMID 25379179, 2014).
squamous cell carcinoma (1 paper, 2014). A carcinoma arising from squamous epithelial cells. "Of the two different NSCLC subtypes, adenocarcinoma (ADC) and squamous cell carcinoma (SCC), we found that PDK4 expression was particularly low in SCC, a subtype lacking good treatment options." (PMID 25379179, 2014).
systemic lupus erythematosus (1 paper, 2025). An autoimmune multi-organ disease typically associated with vasculopathy and autoantibody production. "AIFM1 and PDK4 were notably enriched in pathways related to the cell cycle, complement and coagulation cascades, as well as systemic lupus erythematosus (SLE)." (PMID 40375928, 2025).
viral infection (1 paper, 2020). "This pathway of acetyl-CoA synthesis becomes especially important under conditions of viral infection because PDK4 expression is upregulated leading to PDC inhibition." (PMID 33014275, 2020). "A mechanism through which antioxidant administration protects against viral infection may be through preventing FOXO1 induction of PDK4." (PMID 33014275, 2020).
cancer (130 papers, 2012 to 2025). A tumor composed of atypical neoplastic, often pleomorphic cells that invade other tissues. "PDK4 plays a key role in both metabolic diseases and cancer, and impaired mitochondrial function is one of the causes of several metabolic diseases." (PMID 38671369, 2024). "The mechanisms that dictate the loss of PDK4 during cancer formation need to be fully evaluated in the context of both a wide range of human samples and in mice that allow for conditional or temporal knockout." (PMID 36980540, 2023). "PDK4 upregulation in stromal cells causes elevated cancer aggressiveness, particularly drug resistance, while targeting PDK4 restrains cancer malignancy in vitro, promotes tumor regression in vivo and extends animal post-treatment survival." (PMID 37903887, 2023). "Medium from PDK4+ stromal cells promotes the malignancy of recipient cancer cells in vitro, whereas inhibition of PDK4 causes tumor regression in vivo." (PMID 37903887, 2023). "Prior work indicated that knockout of PDK4 can cause pro-proliferative changes in tumor cells by enhancing lipogenesis in other cancers." (PMID 36980540, 2023). "PDK4 has been found to be over-expressed and implicated in the oncogenesis of many cancers, including that of the colon and bladder." (PMID 36835505, 2023). "Recently, a direct role for PDK4 in promoting cancer-associated muscle metabolic alterations and skeletal muscle atrophy has been reported, and a future study about this enzyme is mandatory." (PMID 34203023, 2021). "PDK4 is also involved in the control of muscle size in cancer stages or after chemotherapy treatment, which renders it interesting as a target to combat cancer-associated cachexia." (PMID 33384955, 2020). "Given the central role that PDK4 plays in regulating the choice between glycolysis and oxidative phosphorylation, PDK4 has been implicated in a number of different cancers." (PMID 22911820, 2012). "Notably, Cox regression analysis, conducted on 33 tumor types, revealed a significant association between PDK4 expression and overall survival in six specific cancers." (PMID 38914792, 2024). "Drugs that target intrinsic metabolic vulnerabilities (e.g., GLUT1 inhibitors, PDK4 inhibitors, or glutaminase inhibitors) predispose cancer cells to death, which is triggered by decreased nicotinamide adenine dinucleotide phosphate generation or increased reactive oxygen species accumulation." (PMID 37842240, 2023). "Given such a pathological relevance, it is reasonable to speculate that PDK4 production by stroma may have a causal role in senescence-related conditions, such as cancer progression." (PMID 37903887, 2023). "In addition, downregulated cancer susceptibility 9 promotes cell apoptosis by the miR-195-5p/pyruvate dehydrogenase kinase 4 axis." (PMID 34261477, 2021). "This loss of PDK4 expression in cancer is more substantial and prevalent than that of most known tumor suppressors, and collectively, these findings suggest that PDK4 may function as a metabolic tumor suppressor, a possibility that would need to be further explored in an in vivo tumorigenesis study." (PMID 25379179, 2014). "PDK4‐mediated metabolic reprogramming antagonizes ferroptosis, synergizing with xCT inhibitors in cancer models." (PMID 40485011, 2025). "Mechanistically, m6A positively regulates glycolysis and ATP generation in cancer cells through pyruvate dehydrogenase kinase 4 (PDK4)." (PMID 40332101, 2025). "In non-cancer cells, RARα/Sp1 enhances induction pyruvate dehydrogenase kinase 4 (PDK4), guanylyl cyclase/atrial natriuretic peptide receptor-A (Npr1), apelin and TNFα-inducible protein 3-interacting protein 1 (TNIP1)." (PMID 39858066, 2025).
cancer (continued). "Given the frequent upregulation of PDK4 in various cancers, ongoing drug research involves investigations involving Cryptotanshinone as a PDK4 inhibitor." (PMID 38672101, 2024). "In the present study, pan-cancer analysis identified PDK4, CCL20, and FBL as central genes (hub genes) with significant differences in expression in 17, 14, and 17 cancer types, respectively." (PMID 38914792, 2024). "For example, our previous study revealed that m6A can positively regulate the glycolysis of cancer cells via regulation of PDK4." (PMID 38549713, 2024). "While both low-grade and high-grade cancers exhibited reductions in PDK4, low-grade tumors had a greater reduction than high-grade tumors." (PMID 36980540, 2023). "Given the lactate-enriched microenvironment formed by PDK4-expressing stromal cells and its effects on cancer cell expression and phenotypes in vitro, we queried the pathological consequences of PDK4 induction in vivo." (PMID 37903887, 2023). "Targeting m6A modifications of oncogenes such as EGFR and MYC can significantly suppress their expression and the proliferation of cancer cells; demethylating metabolic gene PDK4 can reduce its expression and glycolysis of cancer cells." (PMID 36260366, 2023). "The down-regulation of PDK4 allows cancer cells with high TCA cycle/OXPHOS activity to receive more energy for proliferation." (PMID 37863991, 2023). "Among PDK isoforms, PDKs 1–3 interact with various signaling factors enhancing cancer progression and functioning as oncogenes, whereas PDK4 only acts as an oncogene." (PMID 36835086, 2023). "The data suggest a salient capacity of PDK4-expressing stromal cells in reprogramming transcriptomic expression of recipient cancer cells through CM production." (PMID 37903887, 2023). "The demethylation of PDK4 m6A by the dm6ACRISPR system decreased the expression of PDK4 and glycolysis of cancer cells." (PMID 36835633, 2023). "Expression analysis of several cell lines of human prostate origin suggested that stromal cells are indeed more PDK4-inducible than cancer epithelial cells, implying a special mechanism supporting PDK4 production in prostate stromal cells." (PMID 37903887, 2023). "E2F1 and CHEK2 were highly expressed across most cancer types compared to normal samples, while PDK4 and NTRK2 were decreased in various cancers." (PMID 36937870, 2023). "The high expression of CD36, THBS1, and PDK4 in cancer is related to poor prognosis and promotes tumor progression." (PMID 36147333, 2022). "CD36, THBS1, and PDK4 were highly expressed in cancer tissues, whereas PTPRB, G3BP2, and TMEM125 were lowly expressed in cancer tissues." (PMID 36147333, 2022). "Meanwhile, m6A can positively regulate glycolysis in cancer cells by regulating pyruvate dehydrogenase kinase 4 (PDK4), a crucial factor that directs carbon flux from OXPHOS to glycolysis." (PMID 36465351, 2022). "PDK1, PDK2, and PDK3 play a role of tumor promoters, while PDK4 plays a different role in tumor aggressiveness depending on the cancer origin." (PMID 36474273, 2022). "Further studies are required to explore the underlying mechanisms and related proteins to understand the role of PDK4 in multiple types of cancers." (PMID 36362028, 2022). "PDK4 is one of the key factors involved in the regulation of glycolysis in cancer cells, which can promote tumor metabolic remodeling and contribute to chemoresistance." (PMID 35223847, 2022). "Loss of FAM210B caused glycolysis and increased mitochondrial respiration in cancer cells by reducing expression of pyruvate dehydrogenase kinase 4 (PDK4)." (PMID 35832791, 2022). "In the high-PDK4 group, enriched functional pathways were correlated with cell adhesion regulation and synaptic activity, which were substantial in cancer anoikis resistance, proliferation, invasion, and metastasis." (PMID 36685842, 2022).
cancer (continued). "Pyruvate dehydrogenase kinase 4 expression is up-regulated in various cancer tissues, being a suitable target for cancer therapy given its ability to shift glucose metabolism." (PMID 35276978, 2022). "The results revealed that the mRNA and protein expressions of PDK4 were obviously elevated in all cancer cell lines compared with that in the GES-1 cell line." (PMID 35626257, 2022). "PDK4, an important regulator of cellular energy metabolism, was found to be relatively highly expressed in several cancers." (PMID 36478991, 2022). "In our analyses, Cidea and Tmem26 mRNA levels and PGC1α protein levels were increased in the SAT of cancer patients with respect to controls, whereas Pdk4 expression was only slightly increased with respect to controls." (PMID 35454855, 2022). "Many cancers have relatively low PDK4 mRNA in comparison to normal tissues, presumably as a mechanism to negate its anti-proliferative effects." (PMID 34283054, 2021). "Previous reports showed that PDK4 mediated the metabolic switch from glucose metabolism to fatty acid metabolism, and the lower expression of PDK4 increased lipogenesis in cancer tissue." (PMID 33681091, 2021). "Highly expressed CASQ2 and PDK4 were reported to be significantly correlated with poor OS and disease-free survival in cancer patients." (PMID 33833937, 2021). "Pdk4 is a target for Ppara and also considered as a target for cancer detection and therapeutic strategies." (PMID 34202278, 2021). "On the other hand, the commonly downregulated included Pyruvate Dehydrogenase Kinase 4 (PDK4) in 15 cancers and KIT proto-oncogene receptor tyrosine kinase (KIT) in 13 cancers, among the cancers analyzed." (PMID 33801837, 2021). "Therefore, large-scale studies are required to fully dissect the functions of PDK4 in tumor progression and the underlying mechanisms in a variety of human tumor types, which will explain why PDK4 acts as an oncogene or a tumor suppressor gene in various cancers." (PMID 32489458, 2020). "Deletion of Mettl3 decreased the expression of PDK4, while over expression of PDK4 can attenuate Mettl3 regulated glycolysis of cancer cells." (PMID 32444598, 2020). "Based on the metabolic function of the respective tissue, the cancer type and stage, high PDK4 expression can act either oncogenic or tumor suppressive." (PMID 33384955, 2020). "There are several lines of evidence that indicate that PDK4 is involved in cancer progression 14-20." (PMID 32489458, 2020). "Considering that metabolic control by PDK4 is critical for cancer development, the roles of PDK4 in m6A related oncogenic functions in other cancers need further investigation." (PMID 32444598, 2020). "PDK4 regulates glucose metabolism and mitochondrial respiration and can have oncogenic or tumor suppressive effects depending on cancer type." (PMID 33014872, 2020). "The system resulted in about 80% of demethylation and significantly decreased the expression of PDK4 and glycolysis of cancer cells." (PMID 32444598, 2020). "Further, both in vitro and in vivo data suggested that PDK4 was involved in Mettl3 regulated growth and chemosensitivity of cancer cells." (PMID 32444598, 2020). "The crucial role of PDK4 as inhibitor of PDC activity renders it important as a target gene in many cancers and metabolic disorders." (PMID 32323921, 2020). "Targeted specific demethylation of PDK4 m6A by dm6ACRISPR system can significantly decrease the expression of PDK4 and glycolysis of cancer cells." (PMID 32444598, 2020). "Although the promotion roles of PDK4 in cell metabolism have been well illustrated, we further investigated its roles in m6A regulated glycolysis of cancer cells." (PMID 32444598, 2020). "In summary, we provided compelling in vitro and in vivo evidences demonstrating that m6A can regulate the glycolysis of cancer cells via regulation of PDK4." (PMID 32444598, 2020).